PHEX (phosphate regulating endopeptidase X-linked)
Description:
Peptidase that cleaves SIBLING (small integrin-binding ligand, N-linked glycoprotein)-derived ASARM peptides, thus regulating their biological activity. Cleaves ASARM peptides between Ser and Glu or Asp residues. Regulates osteogenic cell differentiation and bone mineralization through the cleavage of the MEPE-derived ASARM peptide. Promotes dentin mineralization and renal phosphate reabsorption by cleaving DMP1- and MEPE-derived ASARM peptides. Inhibits the cleavage of MEPE by CTSB/cathepsin B thus preventing MEPE degradation.
Synonyms: HYP; PEX; HPDR1; HYP1; XLH; HPDR; LXHR
Tractability: Antibody: UniProt places it where antibodies can reach, with high confidence; its Gene Ontology location is reachable by antibodies, with high confidence; UniProt predicts a signal peptide or a membrane-spanning region.
Gene: Protein-coding gene on chromosome X (22,032,325 to 22,494,713, forward strand). Ensembl gene ENSG00000102174.
Subcellular location: Cell membrane
Subcellular location (Human Protein Atlas): Plasma membrane; Vesicles
Gene Ontology:
Molecular function: protein binding; metalloendopeptidase activity; zinc ion binding; metallopeptidase activity
Biological process: proteolysis; cell-cell signaling; protein modification process; protein processing; skeletal system development; bone development; cellular response to parathyroid hormone stimulus; cellular response to vitamin D; lung development; response to growth hormone; response to insulin-like growth factor stimulus; response to sodium phosphate; response to vitamin D
Cellular component: plasma membrane; endoplasmic reticulum; Golgi apparatus; perinuclear region of cytoplasm
Gene-disease validity (ClinGen):
ClinGen rates the evidence that PHEX causes each of these diseases.
X-linked dominant hypophosphatemic rickets (X-linked): Definitive.
Homologues: Orthologues: chimpanzee PHEX (99% identical), macaque PHEX (99% identical), mouse Phex (96% identical), rabbit PHEX (96% identical), guinea pig PHEX (96% identical), rat Phex (96% identical), dog PHEX (95% identical), pig PHEX (94% identical), tropical clawed frog phex (70% identical), zebrafish phex (63% identical), Caenorhabditis elegans nep-25 (16% identical), Drosophila melanogaster Nepl9 (15% identical). Paralogues in human: MMEL1 (38% identical), MME (36% identical), ECE1 (35% identical), ECE2 (33% identical), ECEL1 (30% identical), KEL (23% identical).
Diseases named in the same sentence as PHEX in open-access papers:
PHEX is named in the same sentence as 67 diseases in open-access papers, as found by Europe PMC text mining. Sharing a sentence is not in itself a finding about the gene and the disease. The quoted sentences say what the papers report.
X-linked hypophosphatemia (78 papers, 2011 to 2025). X-linked hypophosphatemia (XLH) is a hereditary renal phosphate-wasting disorder characterized by hypophosphatemia, rickets and/or osteomalacia, and diminished growth. "X-linked Hypophosphatemia (XLH) is a rare genetic disease caused by mutations in the PHEX gene (Xp22.11)." (PMID 40323576, 2025). "X-linked hypophosphatemia is a rare genetic disease caused by pathogenic variants in the PHEX (phosphate-regulating endopeptidase homolog X-linked) gene with X-linked dominant inheritance that causes metabolic bone disease and other severe complications." (PMID 40295317, 2025). "X-linked hypophosphatemia occurs secondary to an inactivating mutation of the phosphate regulating endopeptidase X-linked (PHEX) gene." (PMID 41445552, 2025). "X-linked hypophosphatemia is caused by pathogenic variants in the PHEX gene located on the short arm of the X-chromosome (p22.1–22.2), which is primarily expressed in osteoblasts, osteocytes, and odontoblasts." (PMID 40295317, 2025). "The most common inherited cause of FGF23-mediated hypophosphatemic osteomalacia is X-linked hypophosphatemia (XLH) secondary to a PV of the PHEX gene." (PMID 41445556, 2025). "X-linked hypophosphatemia (XLH) is characterized by lifelong hypophosphatemia caused by excess circulating levels of FGF23 due to loss-of-function mutations in the PHEX gene." (PMID 40486045, 2025). "X-linked hypophosphatemia (XLH) is a rare disorder caused by pathogenic variants in the phosphate-regulating endopeptidase homolog (PHEX) gene that are inherited in an X-linked dominant manner." (PMID 39151033, 2024). "X-linked hypophosphatemia (XLH) is an inherited rickets caused by inactivating mutations in phosphate regulating neutral endopeptidase on the X-chromosome (PHEX)." (PMID 37813865, 2023). "Expression of PHEX (Phosphate-regulating endopeptidase X-linked), which is a gene responsible for X-linked hypophosphatemia, occurs primarily in osteoblast lineage cells." (PMID 36981001, 2023). "The genetic basis of X-linked hypophosphatemia is a loss-of-function mutation in the PHEX gene (Phosphate regulating gene with Homology to Endopeptidases on the X chromosome), which leads to an enhanced production of phosphaturic hormone FGF23." (PMID 36847234, 2023). "A female member of a family where multiple members had renal rickets was tested and identified to have a pathogenic variant in PHEX gene confirming the diagnosis of X-linked dominant hypophosphatemic rickets." (PMID 35123515, 2022). "Inactivating mutations of the gene coding for phosphate-regulating endopeptidase homolog X-linked (PHEX) cause X-linked hypophosphatemia (XLH)." (PMID 36530187, 2022). "Genetic testing revealed a loss-of-function mutation in PHEX (phosphate-regulating gene with homologies to endopeptidases on the X chromosome) which led to a diagnosis of the metabolic bone disease X-linked hypophosphatemia (XLH)." (PMID 34203792, 2021). "The PHEX is the gene whose mutation is the cause of X-linked hypophosphatemia in humans and mice, and their possible sensitivity to stimulation by low phosphorus diets." (PMID 34380559, 2021). "The PHEX protein (coded by a phosphate-regulating gene with homologies to endopeptidases on an X chromosome gene) is associated with X-linked dominant hypophosphatemic rickets (MIM 307800) when mutated." (PMID 34360805, 2021). "The hemizygous Gy male mice with partial deletion of both SMS and downstream gene PHEX (phosphate-regulating endopeptidase homolog, X-linked) was originally used as a model for X-linked hypophosphatemia for defects in phosphate transport." (PMID 29097652, 2017). "Inactivating mutations of the PHEX gene cause X-linked dominant hypophosphatemic rickets (XLHR), which has an incidence of 1:20,000 and is the most common familial form of hypophosphatemic rickets in humans." (PMID 22527485, 2012).
X-linked hypophosphatemia (continued). "Only a few of GSDs having distinct characteristics could achieve an accurate diagnosis, such as X-linked hypophosphatemia (XLH) caused by loss-of-function variants in the PHEX gene." (PMID 37278761, 2023). "Whole-exome sequencing identified a heterozygous deletion in exon 11 of the PHEX gene, consistent with a diagnosis of X-linked hypophosphatemia (XLH)." (PMID 40801029, 2025). "X-linked hypophosphatemia (XLH) is the most common form of hereditary hypophosphatemia and caused by pathogenic variants of the PHEX (phosphate-regulating neutral endopeptidase homolog X-linked) gene." (PMID 40295317, 2025). "Background/Objectives: X-linked hypophosphatemia (XLH) is the most common form of inherited rickets, caused by pathogenic mutations in the PHEX gene (phosphate-regulating endopeptidase homolog, X-linked)." (PMID 41226894, 2025). "Loss-of-function variants in PHEX cause X-linked hypophosphatemia (XLH) (OMIM# 307800), the most common phosphate metabolism disorder, with an estimated prevalence of 1 in 20,000–70,000." (PMID 40282368, 2025). "X-linked hypophosphatemia (XLH) is a hereditary condition caused by mutations in the phosphate-regulating endopeptidase homolog X-linked (PHEX) gene." (PMID 40297179, 2025). "X-linked hypophosphatemia (XLH) is a rare hereditary disorder with an incidence of 3.9 per 100,000 live births and caused by pathogenic variants of the phosphate regulating endopeptidase homolog, X-linked (PHEX) gene." (PMID 40493262, 2025). "X-linked hypophosphatemia (XLH) results from loss-of-function variants in the phosphate-regulating endopeptidase homolog X-linked (PHEX) gene." (PMID 40314226, 2025). "X-linked hypophosphatemia (XLH), caused by mutations in the PHEX gene, disrupts FGF23-mediated phosphate regulation, thereby increasing the risk of OPLL." (PMID 40535334, 2025). "X-linked hypophosphatemia (XLH) is a rare, progressive phosphate-wasting disorder that is caused by loss-of-function variants in the PHEX (phosphate-regulating endopeptidase homologue, X-linked) gene." (PMID 41185884, 2025). "X-linked hypophosphatemia (XLH) is a rare genetic disorder caused by an inactivating mutation in the phosphate-regulating endopeptidase X-linked (PHEX) gene, resulting in elevated levels of the hormone fibroblast growth factor-23 (FGF23)." (PMID 40060917, 2025). "X-linked hypophosphatemia (XLH) is a rare, genetic, phosphate-wasting disorder caused by loss-of-function mutations in the Phosphate Regulating Endopeptidase Homolog X-Linked (PHEX) gene." (PMID 40292234, 2025). "The most frequent subtype is X-linked hypophosphatemia (XLH), caused by pathogenic variants in the PHEX gene, which elevate circulating FGF23 and suppress renal phosphate reabsorption and active vitamin D synthesis." (PMID 41375889, 2025). "X-linked hypophosphatemia (XLH) is a rare, genetic, phosphate-wasting disorder that is caused by loss-of-function variants in the PHEX (phosphate-regulating endopeptidase homologue, X-linked) gene." (PMID 41030383, 2025). "X-linked hypophosphatemia (XLH) is a rare, genetic, progressive, phosphate-wasting disorder that is caused by loss-of-function mutations in the PHEX (phosphate-regulating endopeptidase homologue, X-linked) gene." (PMID 39464774, 2024). "X-linked hypophosphatemia (XLH) is the most common form of inherited hypophosphatemic rickets (HR), caused by pathogenic variants in the PHEX gene." (PMID 39659542, 2024). "X-linked hypophosphatemia (XLH) is the most common form of inheritable rickets (1:20,000) that results from a mutation in the PHEX gene." (PMID 37490334, 2023). "X-linked hypophosphatemia (XLH) is a rare genetic disorder caused by a mutation in the phosphate regulating endopeptidase homolog X-linked (PHEX) gene." (PMID 37026091, 2023). "X-linked hypophosphatemia (XLH), is a disorder that involves a mutation in the Phosphate Regulating Endopeptidase Homolog X-Linked (PHEX) gene, leading to an overexpression of FGF23." (PMID 35899095, 2022).
X-linked hypophosphatemia (continued). "The Hyp mouse is the murine model of human X-linked hypophosphatemia (XLH), with a loss-of-function mutation in the PHEX gene." (PMID 36040459, 2022). "X-linked hypophosphatemia (XLH) is caused by inactivating mutations in the phosphate-regulating endopeptidase homolog, X-linked (PHEX) gene, resulting in an excess of circulating intact fibroblast growth factor-23 (iFGF-23) and a waste of renal phosphate." (PMID 34141703, 2021). "X-linked hypophosphatemia (XLH) is a rare disease caused by inactivating mutations in the phosphate-regulating endopeptidase homolog X-linked (PHEX) gene and characterized by chronic hypophosphatemia." (PMID 31910157, 2020). "X-linked hypophosphatemia (XLH) is a rare hereditary disorder characterized by impaired phosphate homeostasis due to pathogenic variants in the phosphate-regulating endopeptidase homolog X-linked (PHEX) gene." (PMID 41467153, 2025). "Our study underscores the importance of intronic PHEX variants in X-linked hypophosphatemia (XLH)." (PMID 39877728, 2025). "X-linked hypophosphatemia (XLH) is a rare and progressive disease, due to inactivating mutations in the phosphate-regulating endopeptidase homolog X-linked (PHEX) gene." (PMID 40926139, 2025). "X-linked hypophosphatemia (XLH) is a rare genetic disorder characterized by pathological elevations in the serum concentrations of fibroblast growth factor 23 (FGF23) caused by variants of the PHEX gene, leading to low levels of phosphate in the blood." (PMID 40358789, 2025). "The most common genetic cause of FGF23-induced hypophosphatemic osteomalacia is X-linked hypophosphatemia (XLH), secondary to a pathogenic variant (PV) of the PHEX gene." (PMID 41445556, 2025). "X-linked hypophosphatemia (XLHR) is the most common genetic form of hypophosphatemic rickets (HR), which is caused by phosphate regulating endopeptidase homolog X-linked (PHEX) gene mutation." (PMID 38442738, 2024). "An inactivating mutation in the phosphate-regulating endopeptidase homolog X-linked (PHEX) gene, either spontaneous or inherited, is the cause for X-linked hypophosphatemia (XLH; OMIM: 3307800)." (PMID 38818505, 2024). "Phosphate wasting in ARHR2 patients is nearly identical to the phosphate wasting in the prototypic renal phosphate wasting disorder X-linked hypophosphatemia (XLH), due to pathogenic variants in PHEX (phosphate regulating endopeptidase homolog, X-linked)." (PMID 37871131, 2024). "X-linked hypophosphatemia (XLH) is the most common inherited form of rickets, and it is caused by pathogenic inactivating variants of the phosphate-regulating endopeptidase homolog X-linked (PHEX) gene." (PMID 37794959, 2023). "X-linked dominant hypophosphatemic rickets, XLDHR (MIM # 307800) belongs to the FGFR3-dependent rickets category, and it is caused by pathogenic variants in PHEX (phosphate-regulating endopeptidase homolog X-linked)." (PMID 36692815, 2023). "X-linked hypophosphatemia (XLH; OMIM: 3307800) is an inherited disease caused by an inactivating mutation in the phosphate-regulating endopeptidase homolog X-linked (PHEX) gene." (PMID 36051396, 2022). "X-linked hypophosphatemia (XLH), caused by loss-of-function variants of the PHEX gene, located on Xp22.11 and encoding a membrane protein expressed in bone and teeth tissues." (PMID 36371259, 2022). "An inactivating PHEX gene mutation with the resultant accumulation of several mineralization-inhibiting proteins (e.g., FGF23) causes skeletal and dental morbidity in X-linked hypophosphatemia (XLH)." (PMID 36051396, 2022). "X-linked hypophosphatemia (XLH) is an inherited form of rickets, resulting from loss-of-function mutations in the gene for PHEX (Phosphate-regulating gene with Homology to Endopeptidases, located on X-chromosome; specifically, Xp22.1), expressed in bones and teeth." (PMID 36304528, 2022).
X-linked hypophosphatemia (continued). "X-linked hypophosphatemia (XLH) (MIM307800), caused by phosphate-regulating endopeptidase homolog (PHEX) mutations, has also been reported as a cause of modestly elevated axial, though not appendicular, BMD, in both children and adults." (PMID 33193107, 2020). "X-linked hypophosphatemia (XLH) is characterized by rickets and osteomalacia, caused by inactivating mutations in the Phosphate-regulating endopeptidase homolog X-linked (PHEX) gene." (PMID 33072734, 2020). "X-linked hypophosphatemia (XLH) is a rare, lifelong, progressive disease caused by a defect in the PHEX gene, leading to excessive levels of circulating FGF23 with a prevalence rate of around 1 in 20,000." (PMID 32162120, 2020). "In X-linked hypophosphatemia (XLH), PHEX gene variants lead to elevated FGF23 production, resulting in hypophosphatemia, osteomalacia, osteomalacia-related fractures, osteoarthritis, enthesopathy, spinal stenosis, and symptoms of pain, stiffness, and decreased physical function." (PMID 40314226, 2025). "X-linked hypophosphatemia (XLH) is a rare, genetic, progressive, lifelong phosphate-wasting disorder caused by loss-of-function mutations in the PHEX (phosphate-regulating endopeptidase homologue, X-linked) gene, leading to excess circulating levels of fibroblast growth factor 23 (FGF23)." (PMID 39679164, 2025). "X-linked hypophosphatemia (XLH) is a rare, genetic, progressive, lifelong disorder caused by pathogenic variants in the phosphate-regulating endopeptidase homolog, X-linked (PHEX) gene, resulting in excess fibroblast growth factor 23 (FGF23) and consequent renal phosphate wasting." (PMID 40260280, 2025). "We highlight this new mutation among possible causative of X-linked hypophosphatemia and suggest that mosaicism of PHEX mutations is not so uncommon and should be excluded in diagnostic workflow of heritable rickets both in male and female patients." (PMID 36847234, 2023). "X-linked hypophosphatemia (XLH), the most common form of hereditary hypophosphatemic rickets, is caused by inactivating mutations of the phosphate-regulating endopeptidase gene (PHEX)." (PMID 35055123, 2022). "Mineralization defects and paradoxical mineralization of entheses are the hallmarks of X-linked hypophosphatemia (XLH), a rare skeletal disease caused by inactivating mutations in the phosphate-regulating endopeptidase homolog X-linked (PHEX) gene." (PMID 33072734, 2020). "X-linked hypophosphatemia (XLH: OMIM #307,800) is a genetic disease caused by inactivating mutations in the phosphate regulating endopeptidase homolog, X-linked (PHEX) gene, inducing a fibroblast growth factor-23 (FGF23) mediated hypophosphatemia." (PMID 37530996, 2023). "X-linked hypophosphatemia (XLH, MIM #307800) is a rare inherited skeletal disorder caused by mutations in PHEX (phosphate-regulating gene with homologies to endopeptidases on the X chromosome, MIM *300550); the inheritance of XLH follows an X-linked dominant pattern." (PMID 39877728, 2025). "X-linked hypophosphatemia (XLH) is a rare metabolic disorder associated with progressive rickets (XLHR), severe deformities, and osteomalacia, resulting from a loss-of-function mutation in the PHEX gene on the X chromosome." (PMID 38671703, 2024). "X-linked hypophosphatemia (XLH, OMIM 307800) is a rare genetic disease caused by inactivated variants in the PHEX gene, with an estimated prevalence of 1 in 20,000 individuals (phosphate-regulating gene with homologies to endopeptidase on the X chromosome, MIM #300550)." (PMID 38841723, 2024). "X-linked hypophosphatemia (XLH) is caused by an inactivating mutation in the phosphate-regulating endopeptidase X-linked (PHEX) gene whose defective product fails to control phosphatonin fibroblast growth factor 23 (FGF23) serum levels." (PMID 38818505, 2024). "Loss of PHEX activity elevates plasma FGF23 levels, as typical of X-linked hypophosphatemia (XLH)." (PMID 35084563, 2022).
X-linked hypophosphatemia (continued). "X-Linked hypophosphatemia (XLH; Online Mendelian Inheritance in Man (OMIM) #307800) is a rare, genetic and progressive musculoskeletal disease caused by mutations that lead to loss of function of the X-linked homologous endopeptidase (PHEX) gene (OMIM: #300550) that regulates phosphate." (PMID 36553684, 2022). "X-linked hypophosphatemia (also known as X-linked hypophosphatemic rickets, XLH; OMIM: #307800) is an inherited disease of phosphate metabolism, where inactivating mutations of the Phosphate Regulating Endopeptidase Homolog, X-Linked (PHEX, OMIM: #300550) gene lead to local and systemic effects." (PMID 30808384, 2019).